RNU7-170P (RNA, U7 small nuclear 170 pseudogene)
Gene: Small nuclear RNA gene on chromosome 12 (121,908,103 to 121,908,163, forward strand). Ensembl gene ENSG00000239082.
Homologues: Orthologues: chimpanzee U7 (95% identical), macaque U7 (90% identical). Paralogues in human: U7 (89% identical), RNU7-62P (82% identical), RNU7-65P (82% identical), RNU7-48P (80% identical), RNU7-4P (80% identical), RNU7-60P (80% identical), RNU7-81P (80% identical), RNU7-84P (80% identical), RNU7-8P (80% identical), RNU7-11P (79% identical), RNU7-140P (79% identical), RNU7-188P (79% identical), and 143 more.